CDK4 (cyclin dependent kinase 4)
Diseases named in the same sentence as CDK4 in open-access papers (continued):
Sharing a sentence is not in itself a finding about the gene and the disease.
tumor (continued). "CDK4 is a regulator of TNBC BCSC self-renewal and does so, in part, by down-regulating the expression of bone morphogenic protein-4 (BMP-4), a key player in tumor stem cell biology." (PMID 36051751, 2022). "For example, MAPK and cyclin-dependent kinase 4/6 inhibitors act in concert to suppress the proliferation of KRAS-mutant lung cancer cells by triggering the accumulation of NK cells within the tumor and promoting NK cell-dependent tumor cell killing." (PMID 34374809, 2022). "In the last five years, preclinical studies have focused on using small molecule inhibitors targeting cell cycle and DNA damage regulators such as CDK4/6, CHK1 and poly ADP ribosyl polymerase (PARP) to selectively kill tumor cells and enhance cytotoxic immune responses." (PMID 36551637, 2022). "Second, SCLC tumor cells replicate independently of CDK4/6 and trilaciclib will not directly have effects on the tumor." (PMID 36254250, 2022). "However, the CDK4/6-cyclin D-Rb-E2F pathway is hyperactivated in many human cancers, including GBM, resulting in uncontrolled tumor cell proliferation." (PMID 36432068, 2022). "By immunohistochemistry, the tumor cells in both components were immunoreactive for CDK4, but negative for MDM2." (PMID 34089125, 2022). "In preclinical analyses evaluating potential factors contributing to tumor growth in VHL-null Drosophila and human clear cell RCC, synthetic lethality was discovered between VHL and the cell cycle regulators cyclin-dependent kinases 4 and 6 (CDK4/6)." (PMID 36358730, 2022). "Moreover, consistent with the in vitro data, western blot analysis revealed that the effects of ESCCAL-1 overexpression on cell cycle regulators (CDK4, CCND1, and CDKN1A) were partially abolished by knockdown of Gal-1 in ESCC tumor tissues." (PMID 35233069, 2022). "BCL2, CDK4 and MCL1 were highly expressed in all tumours studied." (PMID 35249548, 2022). "Most recently, CDK4/6i has also been demonstrated to promote differentiation of CD8 T cells toward a memory cell fate, which might contribute to enhanced anti-tumor efficacy." (PMID 35248122, 2022). "Dual CDK4 and CDK6 inhibitors have been shown to be active in multiple preclinical models, including xenografts, genetically engineered mouse models and primary human tumor explants." (PMID 35053461, 2022). "One possible explanation is that tumours can adapt to CDK4/6 inhibitors if ESR1 signalling is not correctly suppressed, but, when considering the lack of consensus regarding ESR1 status and CDKi sensitivity, further studies are needed." (PMID 34068388, 2021). "Several CDK4/6 inhibitors have been approved for metastatic breast cancer and phase I/II trials combining MEK or ERK inhibitors with the CDK4/6 inhibitor palbociclib in KRAS-mutant tumours are ongoing." (PMID 34200676, 2021).
tumor (continued). "A recent study suggested that CDK4/6 inhibitors could downregulate DNMT1 expression in Treg cells and trigger anti‐tumor immunity, suggesting that targeting PAX6 might be of clinical value to tumor immunotherapy in the future." (PMID 34459131, 2021). "This dependence on the CDK4 pathway resulted in a potential therapeutic approach to combine MEK and CDK4 inhibitors to target different tumor subpopulations along the EMT spectrum and combat resistant outgrowth of epigenetic subsets in a heterogeneous tumor." (PMID 34309585, 2021). "Dual inhibition of CDK4/6 and HSP90 suppresses tumor growth in vivo." (PMID 34686682, 2021). "Our data demonstrated that overexpression of FHL1 inhibited the proliferation, colony formation potential, and expression of CdK4 and Cyclin D1, whereas ablating FHL1 promoted proliferation and colony formation potential, suggesting that FHL1 acts as a tumor suppressor in CRC." (PMID 34335951, 2021). "In heterogeneous tumors, with a mix of plastic epithelial and mesenchymal cancer cells, net tumor killing requires drug combinations that preferentially target the vulnerabilities of each subpopulation (e.g., MEK inhibitors and CDK4 inhibitors) and prevent the outgrowth of resistant cells." (PMID 34309585, 2021). "Further, these studies suggest that inhibition of CDK4 and CDK6 could be exploited to specifically control the proliferation of tumor cells that rely on their activity." (PMID 34204543, 2021). "This is in line with previous studies by others and us, where different tumors and tumor cell lines have been reported to be sensitive to PI3K and FGFR inhibitors, despite not having PI3K, CDK4/6, and or FGFR mutations." (PMID 34631586, 2021). "Adding palbociclib, a CDK4/6 inhibitor, to MLN0128, could even potentiate its anti-tumor effects for iCCA making dual kinase inhibition of mTORC1/2 a promising treatment strategy for CCA." (PMID 35096817, 2021). "The response to palbociclib was significantly reduced by RABL6A depletion in the tumor cells, suggesting that patient MPNSTs bearing elevated RABL6A may be more responsive to CDK4/6 inhibitor therapy." (PMID 33456709, 2021). "For example, CDK4/6 inhibitors in combination with gemcitabine improved antitumor activity without G1 cell cycle arrest in calu-6 xenografts tumor-bearing mice." (PMID 34395246, 2021). "From this list, we selectively validated CDK4 amplifications using fluorescence in situ hybridization (FISH) and confirmed that cells carrying high‐level gains were ubiquitously present in all analyzed tumor sections." (PMID 33963544, 2021). "Our data demonstrated that overexpression of FHL1 inhibited the proliferation, colony formation potential, and expression of CdK4 and Cyclin D1, whereas ablating FHL1 promoted their proliferation and colony formation potential, suggesting that FHL1 acts as a tumor suppressor in CRC." (PMID 34335951, 2021). "Since CDK4 is activated by CCND1, recent studies have shown that it is also overexpressed in several cancer types and shares similar oncogenic characteristic with CCND1 in tumor tissues." (PMID 34063946, 2021). "The results showed that upregulation of circACTN4 could increase the expressions of MYC, CDK4, CCND2 and Ki67 in tumor tissues, whereas circACTN4 silencing reduced the expression levels of these proteins." (PMID 34116677, 2021). "Additionally, the triple combination of CDK4/6, PI3K and immune-checkpoint blockage demonstrated long-lasting anti-tumor activity against TNBC in vivo." (PMID 33599863, 2021). "Key kinases regulating cell cycle G1 progression were also altered in different CTC samples including cyclin-dependent kinase 6 (CDK6, chr7) gain in CTC 1 of P43 and in single CTCs of P50, and cyclin-dependent kinase 4 (CDK4, chr12) gains in 5/7 CTCs of P45 and the corresponding tumor biopsy." (PMID 34272470, 2021).
tumor (continued). "While CDK4/6i increases B-galactosidase staining (indicative of senescence), no other SASP genes are induced, suggesting that senescence does not contribute to CDK4/6i-induced tumor immunogenicity." (PMID 34025662, 2021). "Although the difference between the standard combination of fulvestrant and CDK4/6i and triple combination treatment was not significant, a smaller mean of tumor volume and weight were observed for the triple combination group." (PMID 34433817, 2021). "Analysis of circulating tumor DNA of patients in the PALOMA-3 trial displayed that there are two distinct types of resistance that can arise due to combination treatment of antiestrogens and CDK4/6 inhibitors." (PMID 34830174, 2021). "In summary, the small molecules induced degradation of BTK, CDK4/6, BCR-ABL and BRAF in cancer cells had a better anti-tumor cell proliferation effect than simply inhibiting, and they also demonstrated promising power in overcoming tumor drug resistance." (PMID 34249939, 2021). "CDKN2A could inhibit the tumor-promoting behavior of CDK4/6, and given that the CDKN2A alteration is frequent in HCC, CDK4/6 inhibitors are presently being tested in advanced HCC." (PMID 33407585, 2021). "Similarly, CDK4/6i can resensitize therapy-resistant tumors to EGFR inhibitors, MET/TRK inhibitors, and MEK inhibitors by suppressing the growth of tumor cells in multiple pre-clinical models, in vitro and in vivo." (PMID 33809714, 2021). "Excitingly, more pronounced tumor growth inhibition is observed (131% TGI) in the MCF7 xenograft model, accompanied by significant reductions in ER protein levels when combined with a CDK4/6 inhibitor palbociclib." (PMID 34025443, 2021). "However, the possible radiosensitizing effects of the cyclin-dependent kinase 4 (CDK4) and cyclin-dependent kinase 6 (CDK6) inhibitor palbociclib are not limited to tumor cells alone, but can also affect healthy cells." (PMID 34722291, 2021). "Recent studies have found that CDK4/6i, which inhibit the cell cycle, can inflame the TIM of HR + BC by repressing Tregs and increasing the infiltration and activation of antitumor immune cells within tumor." (PMID 33413549, 2021). "These favorable effects, however, could be due, at least in part, also to other antitumor immunity-promoting effects that have been observed with CDK4/6 inhibitors such as increased production of type III interferons and enhanced tumor antigen presentation." (PMID 33921301, 2021). "It is therefore not surprising that the combination of CDK4/6 inhibitors and anti‐PD‐L1 therapy led to substantial tumor regression in xenograft mouse models." (PMID 34977872, 2021). "A cell cycle-dependent kinase CDK4/6 inhibitor, palbociclib (PAL), was selected in the current study because we previously reported that this cell cycle inhibitor could suppress NPC tumor growth in an NPC PDX animal model." (PMID 34204797, 2021). "Another important study demonstrated that CDK4/6 inhibition blocks the tumor metastasis potential of multiple preclinical models of TNBC without affecting primary tumor growth." (PMID 33599863, 2021). "More specifically, several studies reported that increased expression of S100A6 promoted cell proliferation by regulating the expression of IL‐8, CDK5, CDK4, MCM7, Bcl2, and could be used as a marker of tumor aggressiveness in gastric cancers." (PMID 34857857, 2021).
tumor (continued). "It is possible that this is due to the fact that olaparib is involved in inducing tumor cell death, without directly interfering with the cell cycle, differently from other target agents such as CDK4/6-inhibitors." (PMID 34262869, 2021). "In addition, cell cycle–related proteins, including CDK4/CDK6 and cyclin D1 were up-regulated upon tumor onset in thymi harboring small tumors, which was maintained in end-stage tumors for most of the samples tested." (PMID 33310759, 2021). "Thus, mitogenic signals suppress ERVs expression via DNA methylation, mediated by the CDK4/6-Cyclin D-Rb-DNMT1 axis, and inhibition of this axis results in ERVs activation followed by enhanced anti-tumor immunity." (PMID 33668131, 2021). "CDK4/CDK6 inhibitors possibly instigate an antitumor immune response by the stimulation of the T lymphocyte activation effector, reduce T cell proliferation, and enhances tumor cell antigen presentation." (PMID 34361615, 2021). "This tumor carried wild-type RB1, which is essential for CDK4/6 inhibitor sensitivity." (PMID 33580196, 2021). "Cotargeting CDK4 and MAPK pathways targets different tumor cell subsets." (PMID 34309585, 2021). "Evidence from past studies indicated that CDK4 depletion reduced infiltration of CD4+FoxP3+ Tregs, and CDK4 inhibitors increased tumor immunogenicity and cytotoxic T cell–mediated clearance of tumor cells." (PMID 34309585, 2021). "Moreover, miR-874 targets serine-threonine kinase cyclin-dependent kinase 4 (CDK4), a tumor oncogene." (PMID 34722778, 2021). "In addition to the previously identified germline BRCA alteration in this case, CDK4 and MYC copy number alterations were identified by NGS of matched tumor-normal tissue, informing subsequent treatment decisions." (PMID 33619265, 2021). "Although CDK4/6i treatment increased immune infiltration as well as T cell activity, monotherapy did not achieve continuous tumor suppression during treatment." (PMID 32929370, 2020). "In addition to intersecting with ER, PI3K, and RAS pathways, the cyclin D-CDK4/6-RB pathway is also involved in DNA damage repair (DDR), which makes CDK4/6 inhibitors perfect candidates for tumor radiosensitization." (PMID 32933570, 2020). "The expression levels of AKT, p-AKT Ser 473, GSK 3β, p-GSK 3β Ser 9, CDK4, and cyclin D1 in tumor tissue removed from the mouse groups treated or not treated with 6-gingerol were measured next." (PMID 31832810, 2020). "Copy number analysis indicated gain in CDK4 (25.7%) and CDK6 (14.7%) in CCA tumor samples." (PMID 33116269, 2020). "Considering their potential for tumor promotion, strategies to address TIS and the SASP may be the key to improving the anticancer efficacy of CDK4/6 inhibitors." (PMID 33116117, 2020). "By immunohistochemistry, tumor cells demonstrated strong nuclear cyclin D1 expression and multifocal smooth muscle actin staining but were negative for MUC4, ERG, CD34, S-100 protein, desmin, STAT6, CD45, MDM2, CDK4, ALK, and ROS1." (PMID 32461620, 2020). "As an inhibitor of the Cyclin-Dependent Kinase 4/6 (CDK4/6), the Cyclin-Dependent Kinase Inhibitor p16 (p16) has regulatory roles of CDK4/6 in cell cycle G1 progression 1,which is also known as a vital tumor suppressor." (PMID 32047552, 2020). "Myoblasts with the oncogenes CDK4 and hTERT do not develop tumors in mice, which means that the combination of these two oncogenes is not sufficient for tumor inception." (PMID 32438562, 2020). "Our results were consistent with those from in vivo experiments, that is, dramatic decreases in class I HDACs, CDK4, cyclin D1, Ki-67, and EMT-promoted protein expression and increased p21 and E-cadherin expression in tumor tissues of mice treated with magnolol or MM1." (PMID 32850418, 2020). "Abnormal Rb regulation in tumor cells manifested with overexpressed CDK4/CDK6 and the loss of p16 expression or CDK4/CDK6 mutation leading to no response to p16." (PMID 32860670, 2020).
tumor (continued). "Proteins from transplanted tumor tissues were extracted for Western blot analysis, and the results displayed that levels of FTO, MYC, CDK2, CDK4, Ki-67, PCNA and Bcl-2 proteins in miR-96 antagomir group were downregulated, while AMPKα2 and Bax proteins were raised." (PMID 33183350, 2020). "Furthermore, safranal-treated tumor tissues exhibited a reduction in Skp2, E2F1, NF-κB p65, p-IκBα (Ser32), c-MYC, p-Rb (Ser807), CDK4, CDK6, and CDK2 and an elevation of p27 and p21 protein levels." (PMID 33392189, 2020). "Additionally, numerous targets of expressions which were observed in carcinogenesis and tumor progression were reported to be regulated by miR-34a, such as CD44, BCL2, NOTCH1, CDK4/6, MET, MYC, and many other molecules." (PMID 32391256, 2020). "EZH2-mediated PRC2 activation contributes to the transcriptional silencing of tumor suppressor genes, leading to the activation of NOTCH, JAK-STAT, or β-catenin signaling pathways and upregulation of cell cycle genes, such as CDK2, CDK4, and CCND1." (PMID 33121524, 2020). "Therefore, we examined the effects of FBX8/HIF-1α, FBX8/CDK4, and FBX8/C-Myc, on tumor angiogenesis, cell cycle progression, cell proliferation, and stem cell potential, respectively." (PMID 32796813, 2020). "Pathological analysis revealed no malignant tumor cells, and immunohistochemical staining for CDK4 and MDM2 yielded negative results." (PMID 33228609, 2020). "The final pathological analysis showed no malignant tumor cells and negative immunohistochemical staining results for CDK4 and MDM2; therefore, ruling out a diagnosis of the low-grade malignant bone tumor." (PMID 33228609, 2020). "PFS in patients undergoing endocrine therapy plus CDK4/6i was inversely correlated with Ki67 expression but not with PR, suggesting that tumor proliferation has a greater impact on cell cycle inhibitors combined with endocrine therapy than PR expression." (PMID 32784518, 2020). "In addition to an MDM2 amplification, copy number analyses also revealed amplification of CDK4 in three tumors (cases 1–3) and a deletion of CDKN2A in one tumor (case 5)." (PMID 32352245, 2020). "In addition, depletion of CDK4/6 activity by treatment with Lee011 and shRNA knockdown was used to verify that CDK4/6 inhibition reversed the EMT phenotype and prevented tumor cell metastasis through the regulation of ZEB1 in vitro." (PMID 32296027, 2020). "Collectively, these data support the anti-tumor activity of elacestrant in models derived from patients that have been treated previously with a CDK4/6i (in combination with an AI/fulvestrant) and in PDX models that are innately resistant to CDK4/6i." (PMID 31852484, 2019). "In this regard, inhibition of CDK4/6 in cancer cells reduces the levels of the anti-oxidants NADPH and glutathione, stabilizes the immunosuppressive ligand PD-L1, stimulates tumor antigen presentation, and hyperactivates proteasomal function." (PMID 30692638, 2019). "Importantly, RN181 expression is inversely correlated with the expression of cyclin D1 and CDK4 in GC clinical samples, substantiating the role of the RN181–cyclin D1/CDK4 pathway in control of the tumour growth of GC." (PMID 30714150, 2019). "In clinical trials, monotherapy with CDK4/6 inhibitors has failed to provide long-term anti-tumor effects in almost all tumor entities examined, mostly due to de novo and acquired resistance mechanisms." (PMID 31331377, 2019). "To test if CDK4/6 inhibition combined with MET inhibition is a feasible strategy for cancer treatment in vivo, we assessed the combined effect of crizotinib and palbociclib on the growth of human tumour xenografts in athymic mice." (PMID 31296956, 2019). "Importantly, in clinical tumour samples, RN181 was reversely correlated with the expression of cyclin D1 and CDK4, highlighting the role of the RN181–cyclin D1/CDK4 pathway in the control of tumour growth." (PMID 30714150, 2019).